MAGEC2 (MAGE family member C2)
Diseases named in the same sentence as MAGEC2 in open-access papers:
MAGEC2 is named in the same sentence as 51 diseases in open-access papers, as found by Europe PMC text mining. Sharing a sentence is not in itself a finding about the gene and the disease. The quoted sentences say what the papers report.
melanoma (36 papers, 2010 to 2025). A malignant, usually aggressive tumor composed of atypical, neoplastic melanocytes. "In HCC patients, MAGEC2 correlated with increased tumourigenesis and was associated with poor prognosis, with similar findings reported in breast cancer patients and melanoma patients." (PMID 36649303, 2023). "MAGEC2, has been shown to be aberrantly expressed in squamous cell carcinomas, melanomas, sarcomas, myelomas, hepatocellular carcinomas, lung carcinoma, prostate adenocarcinoma, and breast carcinoma." (PMID 35355564, 2022). "The expression of the melanoma/cancer-testis antigen MAGEC2/CT10 is restricted to germline cells, but like most cancer-testis antigens, it is frequently upregulated in advanced breast tumors and other malignant tumors." (PMID 35355564, 2022). "We demonstrate that MAGEC2 interacts with TRIM28 in melanoma cells and MAGEC2 expression in tumor cells depends on the expression of TRIM28." (PMID 30309319, 2018). "For example, expression of MAGEC2 in primary melanoma is a potential predictor of metastasis; MAGEC2 expression in breast cancer is correlated with poor clinical prognosis." (PMID 30309319, 2018). "Melanoma cells were identified by MAGEC2 and Melan‐A staining." (PMID 37679999, 2023). "In this study, we found that expression of MAGEC2 protein in tumor cells depends on the expression of TRIM28, a reduction in the level of endogenous TRIM28 expression in melanoma cells resulting in significantly decreased expression of MAGEC2 protein." (PMID 30309319, 2018). "MAGEC2 was shown to interact with STAT3 and inhibit its polyubiquitination and proteasomal degradation in human and mouse melanoma cell lines (i.e., A375 and B16, respectively)." (PMID 29914167, 2018). "MAGEC2 (also known as HCA587), a member of MAGE family, is a CT antigen expressed in tumors of various histological types, including hepatocellular carcinoma, melanoma, lung cancer, bladder cancer and breast cancer etc.." (PMID 30309319, 2018). "We undertook a mutational analysis of coding regions of four CT-X MAGE genes, MAGEA1, MAGEA4, MAGEC1, MAGEC2 and the ubiquitously expressed MAGEE1 in human melanoma samples." (PMID 20862285, 2010). "In addition, the interaction between endogenous MAGEC2 and TRIM28 was also detected in another human melanoma cell line Hs 695 T." (PMID 30309319, 2018). "To determine whether TRIM28 expression is regulated by MACEC2 expression in tumor cells, we also detected the expression level of TRIM28 in MAGEC2-knockdown melanoma cells and no change was observed, suggesting that TRIM28 expression level is not regulated by MAGEC2." (PMID 30309319, 2018).
breast carcinoma (9 papers, 2012 to 2024). "Consistent with the molecular heterogeneity of breast cancer, this analysis revealed that high Ca2+-induced expression of early response genes FOS/FOSB as well as genes associated with malignant tumors such as MAGEC2 was cell type specific." (PMID 35355564, 2022). "MAGEC2 has recently been reported to bind to TRIM28 in breast cancer cell lines HTB126 and HCC1806." (PMID 30309319, 2018). "However, no humoral response was observed against SSX-4, MAGE-3, MAGEC1 and MAGEC2 in breast cancer." (PMID 23451156, 2013). "Overall, this study suggests that the aberrant expression of MAGEC2 and presumably related cancer-testis antigens in malignant solid tumors is triggered at least in part by the gradual increase in circulating Ca2+ that develops as breast cancer progresses to more malignant stages." (PMID 35355564, 2022).
hepatocellular carcinoma (9 papers, 2011 to 2024). A malignant tumor that arises from hepatocytes. "MAGEC2 expression has been observed in advanced stages of different tumours, including myeloma and hepatocellular carcinoma (HCC), and is usually associated with poor prognosis." (PMID 36649303, 2023). "Immunohistochemistry (IHC) staining was performed in hepatocellular carcinoma patients to evaluate the association between the expression of MAGEC2 and TRIM28." (PMID 30309319, 2018). "MAGEC2 promotes metastasis in human hepatocellular carcinoma cells by reducing the ubiquitin-mediated proteolysis of p-STAT3." (PMID 32116696, 2020). "Distribution of TRIM28 expression level in MAGEC2-positive and MAGEC2-negative tissues of hepatocellular carcinoma patients." (PMID 30309319, 2018). "Human hepatocellular carcinoma tissues were immunohistochemically stained with anti-MAGEC2 or anti-TRIM28 antibodies, and H score was assigned to each sample for MAGEC2 and TRIM28, respectively." (PMID 30309319, 2018). "Furthermore, expression levels of MAGEC2 and TRIM28 are positively correlated in MAGEC2-positive human hepatocellular carcinoma tissues (p = 0.0011)." (PMID 30309319, 2018). "We detected the expression of MAGEC2 and TRIM28 in human hepatocellular carcinoma (HCC) as MAGEC2 was reported to be more frequently overexpressed in HCC tissues." (PMID 30309319, 2018).
lung carcinoma (6 papers, 2018 to 2025). "The same effect was observed when we evaluated a different antigen tested in a lung cancer mRNA vaccine, MAGEC2." (PMID 38380261, 2024). "To determine whether TRIM28 affects the induced expression of MAGEC2 in tumor cells, we treated MAGEC2-negative human lung cancer cells A549 with demethylating agent 5-aza-2-deoxycytidine (5-aza) in the presence or absence of TRIM28." (PMID 30309319, 2018). "MAGEC2-negative cell lines, human lung cancer cells A549 and pancreas cancer cells AsPC1, were treated with 5-aza, and the expression of MAGEC2 was induced in A549, but not in AsPC1 cells." (PMID 30309319, 2018).
multiple myeloma (6 papers, 2011 to 2024). "MAGEC2 promotes proliferation and resistance to apoptosis in multiple myeloma." (PMID 35743282, 2022). "For example, MAGEC2 promotes proliferation and resistance to apoptosis in multiple myeloma." (PMID 35743282, 2022).
prostate carcinoma (6 papers, 2011 to 2024). A carcinoma that arises from epithelial cells of the prostate gland. "Detection of MAGEC2/CT10 in patient tissues has also been shown to be an independent predictor of lymph node metastasis and recurrence of prostate cancer." (PMID 35355564, 2022). "The differentially expressed gene-list contained various genes previously reported to be differentially expressed in low- and intermediate/high-grade prostate cancer such as HOXC6, MAGEC2, HERPUD1 and SATB1." (PMID 27191985, 2016).
non-small cell lung carcinoma (3 papers, 2023 to 2024). A group of at least three distinct histological types of lung cancer, including non-small cell squamous cell carcinoma, adenocarcinoma, and large cell carcinoma. "MAGEC2, which is highly expressed in non-small cell lung cancer cells, promotes angiogenesis and EMT." (PMID 37834126, 2023).
leukemia (2 papers, 2011 to 2022). A malignant (clonal) hematologic disorder, involving hematopoietic stem cells and characterized by the presence of primitive or atypical myeloid or lymphoid cells in the bone marrow and the blood. "We are interested in how MAGEC2 expression is regulated in K562 leukemia cells." (PMID 35743282, 2022). "Therefore, the overexpression of miR-874 mimic or immuno-targeted MAGEC2 might be another approach to leukemia therapy." (PMID 35743282, 2022).
Gynecomastia (1 paper, 2020). Abnormal development of large mammary glands in males resulting in breast enlargement. "MAGEA family members, in particular MAGEA2, MAGEA11, and MAGEC2, showed the hypomethylation of several CpGs (p < 0.01) in MBC compared to gynecomastia." (PMID 32626651, 2020).
Hypercalcemia (1 paper, 2022). An abnormally increased calcium concentration in the blood. "Further studies are also warranted to validate MAGEC2 and other high Ca2+-inducible genes as biomarkers for hypercalcemia modulated cancer progression and metastasis." (PMID 35355564, 2022).
invasive ductal carcinomas (1 paper, 2022). "This is supported by our TCGA data analysis showing an increase in the expression of MAGEC2 in invasive ductal carcinomas compared to normal breast tissues." (PMID 35355564, 2022). "To assess the clinical relevance of this finding, we show that MAGEC2 is significantly upregulated in invasive ductal carcinoma tissues compared to normal breast tissues according to TCGA Breast dataset in oncomine." (PMID 35355564, 2022).
leiomyosarcoma (1 paper, 2024). An uncommon, aggressive malignant smooth muscle neoplasm, usually occurring in post-menopausal women. "The most overexpressed and underexpressed genes in CP0024 leiomyosarcoma cell cultures transduced with shHMGA1 were DCT (logFC = 1.607; adjusted p-value < 0.001), and MAGEC2 (logFC = − 2.091; adjusted p-value < 0.001), respectively." (PMID 38758230, 2024).
cancer (45 papers, 2011 to 2025). A tumor composed of atypical neoplastic, often pleomorphic cells that invade other tissues. "We also noticed increased expression of the EMT activator ZEB1, the tumor-associated antigens MAGEA3/A6 and MAGEC2, and metalloproteinase in EMThi cancer cells." (PMID 35503263, 2022). "Accumulating evidence has indicated that MAGEC2 expression is associated with hallmarks of aggressive cancers." (PMID 30309319, 2018). "Furthermore, high extracellular Ca2+ also stimulated the expression of early response genes such as FOS/FOSB and a unique set of genes associated with malignant tumors, including MAGEC2." (PMID 35355564, 2022). "Based on the microarray data, we speculated that the expression of early response FOS and/or FOSB may lead to the expression of cancer progression associated genes such as MAGEC2." (PMID 35355564, 2022). "We sought to understand how MAGEC2 specifically recognizes TRIM28 as this will provide a strategy to target MAGEC2 in various cancer therapeutics." (PMID 38448672, 2024). "We sought to test the role of this PBG in another MAGE protein, MAGEC2, the expression of which is a poor prognostic marker in many cancers and which also acts as an oncogene." (PMID 38448672, 2024). "One network comprises well known cancer antigens (e.g. GAGE1, MAGEB2, MAGEC2 and SSX1) associated with short overall survival and additional aggressive tumour properties." (PMID 36649303, 2023). "Data from this study suggests for the first time that the aberrant expression of MAGEC2 and presumably related cancer-testis antigens in malignant solid tumors is triggered at least in part by high circulating Ca2+." (PMID 35355564, 2022). "Recent studies revealed the oncogenic properties of MAGEC2 in facilitating cancer cell viability, proliferation and metastasis." (PMID 30309319, 2018). "Three of these mRNAs encode cancer testes antigens (NY-ESO-1, MAGEC1, and MAGEC2) which are normally only expressed in male germ cells but are often also expressed in tumors including NSCLC, making them an attractive target for cancer vaccines." (PMID 25288198, 2014). "Moreover, the same effect was observed when we introduced iPLUSv2 downstream of MAGEC2, a tumor-specific antigen tested for cancer mRNA vaccines." (PMID 38380261, 2024). "Moreover, the impact of iPLUSv2 in MAGEC2 bears substantial implications for its application in cancer mRNA vaccines, as the increase in antigen production certainly influences the efficiency of the process." (PMID 38380261, 2024). "Overall, this study suggests for the first time that the aberrant expression of MAGEC2 that is frequently observed in malignant solid tumors may at least in part be mediated by a cancer-induced increase in circulating Ca2+." (PMID 35355564, 2022). "What controls or regulates the expression of MAGEC2 in cancer cells remains largely unknown to date." (PMID 30309319, 2018). "In addition, it has been reported that the miR-874 could directly bind to 3′UTR of MAGEC2 and destabilize RNA in cancer cells." (PMID 35743282, 2022). "However, little is known for the regulation of MAGEC2 expression in cancer cells." (PMID 30309319, 2018). "Of 90 CTAs validated by RNA sequencing, eight CTAs (DPEP3, EZHIP, MAGEA4, MAGEB2, MAGEC2, PAGE1, PRAME, and TKTL1) were selected for immunohistochemical profiling in cancer tissues from 328 NSCLC patients." (PMID 37341056, 2023). "Two protein-protein interaction networks were observed for genes upregulated in solid cancer: one network included products of cancer-specific genes such as MAGEB2, MAGEC2 and SSX1 for the whole cohort." (PMID 36649303, 2023). "The cancer–testis antigens contains 44 proteins (including LAGE1, MAGEC2, NY-ESO-1), the expression of which is characteristically restricted to cancer and the human germ line." (PMID 35668458, 2022).
cancer (continued). "Several cancer biomarker genes were downregulated following treatment in responders, including MLANA (log2 fold change = − 4.19; p = 0.0617) and MAGEC2 (log2 fold change = − 5.19; p = 0.0308)." (PMID 33407577, 2021). "Genes such as MAGEA3 and MAGEA6 contributed targets for 7 cancer types each, while genes such as UMODL1, NLRP4, MAGEC2, ANKRD30A, and GPRC6A contributed targets for only 1 cancer type." (PMID 27439771, 2016). "Interestingly, known CTAs, such as MAGEA3, MAGEA1, DSCR8, MAGEC2, and MAGEA6, tended to be identified in the largest number of cancer types." (PMID 39561714, 2024). "Our findings show that TRIM28 is necessary for MAGEC2 expression in cancer cells, and TRIM28 may serve as a new potential target for immunotherapy of cancer." (PMID 30309319, 2018). "Our findings for the first time revealed that the expression of cancer testis antigen MAGEC2 in tumor cells depends on the existence of TRIM28, which is very important for further exploring the biological functions of MAGEC2 and TRIM28 in tumorigenesis and cancer development." (PMID 30309319, 2018). "In addition, as an important positive regulator of MAGEC2, TRIM28 might be a potential target for cancer therapy." (PMID 30309319, 2018).
tumor (38 papers, 2011 to 2025). "Among the tumor samples with positive staining results, 82% (41/50) were inferred to express the MAGEC2 gene based on RNA-seq data." (PMID 39561714, 2024). "This is the case of MAGEC2, a cancer-testis antigen that is known to be aberrantly expressed in highly malignant breast and other neoplasms." (PMID 35355564, 2022). "Mechanistic studies indicate that the regulatory role of TRIM28 on MAGEC2 protein expression in tumor cells depends on proteasome-mediated pathway." (PMID 30309319, 2018). "In vivo, intravenously injected MAGEC2-overexpressing B16 cells and MAGEC2-knockout A375 cells generated, respectively, more and less tumor nodules in the lungs of mice compared with parent cells." (PMID 29914167, 2018). "Cancer/testis antigen MAGEC2 (also known as HCA587) is highly expressed in a wide variety of tumors and plays an active role in promoting growth and metastasis of tumor cells." (PMID 30309319, 2018). "Depletion of TRIM28 expression in tumor cells not only reduced the endogenous expression level of MAGEC2 protein, but also decreased the exogenous expression of MAGEC2 protein." (PMID 30309319, 2018). "We further detect the effects of knockdown or overexpression of TRIM28 on the levels of exogenous expression of MAGEC2 protein in tumor cells." (PMID 30309319, 2018). "Interestingly, high extracellular Ca2+ transiently induced the expression of early response genes that in turn induced the expression of genes including MAGEC2 that drive the growth and motility of the tumor cells." (PMID 35355564, 2022). "It is possible that the survival of Ca2+ adapted cells may be sustained by high Ca2+ inducible expression of genes that influence tumor cell growth and/or motility such as MAGEC2." (PMID 35355564, 2022). "As MAGEC2 is a cancer-testis antigen that is normally expressed in testis but aberrantly expressed in a broad spectrum of tumors, significant effort has been directed toward exploring its potential in tumor immunotherapy." (PMID 30309319, 2018). "Expression levels of TRIM28 and MAGEC2 are detected in different tumor cell lines." (PMID 30309319, 2018). "Here, we found that expression of MAGEC2 protein in tumor cells requires the existence of TRIM28." (PMID 30309319, 2018). "However, little is known about the regulation of MAGEC2 expression in tumor cells except that it is a direct target of miR-874." (PMID 30309319, 2018). "In this study, we also found that the regulatory role of TRIM28 on the expression of MAGEC2 protein in tumor cells is proteasome-dependent, which may be related with the E3 ubiquitin ligase activity of TRIM28." (PMID 30309319, 2018). "Up regulation of MAGEC2 and other high Ca2+ inducible genes that influence the growth and motility of tumor cells may be invaluable in the adaptation of tumor cells to high Ca2+ as depletion of this gene strongly attenuated the growth of the cells in either normal or high Ca2+ conditions." (PMID 35355564, 2022). "First, we found multiple MAGE family proteins (e.g., MAGEC2, MAGEB2, MAGEC1, MAGEB6) with a gene expression profile similar to those in clinical trials (MAGEA1, MAGEA4), which have been reported to be tumor specific." (PMID 39515334, 2024). "CT47A1, PAGE1, MAGEA9, MAGEC2, and MAGEA1 were detected at protein level in tumor tissues (CT47A1 in 14%, PAGE1 in 23%, MAGEA9 in 11%, MAGEC2 in 59% and MAGEA1 in 34% of tumors)." (PMID 34065388, 2021). "MAGEC2 was detectable in 26/53 (42.4%) cases, while TRIM28 was observed in almost all tumor samples." (PMID 30309319, 2018). "Co-immunoprecipitation assay was applied for detecting the endogenous interaction of MAGEC2 and TRIM28 in tumor cells." (PMID 30309319, 2018). "Genes involving the extracellular space and plasma membrane regulators were increased in aggressive MSI‐H CRC tumors, and tumor antigens (MAGEA3, MAGEA6, MAGEA9B, or MAGEC2) involving in the transcriptional and post‐translational regulations were represented in the aggressive MSI‐H signature." (PMID 39322998, 2025).
tumor (continued). "The expression level of MAGEC2 protein was significantly reduced when TRIM28 was depleted in tumor cells, and no changes were observed in MAGEC2 mRNA level." (PMID 30309319, 2018). "There were 10 lncRNAs that were expressed in more than 20% of the tumor samples (LINC01980, AC025254.1, LINC02806, LINC02476, LINC02506, AL162413.1, LINC00221, LINC01287, AC079466.1, and LINC01419), compared to five protein-coding genes (MAGEA1, MAGEA3, SSX1, DCAF4L2, and MAGEC2)." (PMID 38985879, 2024).
blood cancer (1 paper, 2023). "Notably, upregulated genes in short survival cases across solid and blood cancer cohorts include a common immune gene signature comprising MAGEC2, SSX1 and ULBP2." (PMID 36649303, 2023). "Three upregulated genes were common to both solid and blood cancers (MAGEC2, SSX1, ULBP2), but there were no common downregulated genes." (PMID 36649303, 2023).
MAGEC2 also shares sentences with these, for which no sentence is quoted: bladder urothelial carcinomas (3 papers); esophageal squamous cell carcinoma (3); gastrointestinal stromal tumor (3); bladder cancer (2); breast tumors (2); colorectal cancer (2); cutaneous melanoma (2); head and neck cancer (2); lung adenocarcinoma (2); lymph node metastasis (2); mucosal melanoma (2); pancreatic cancer (2); seminoma (2); triple-negative breast carcinoma (2); anal melanoma (1); benign prostatic hyperplasia (1); bladder tumors (1); cardiovascular diseases (1); chronic myeloid leukemia (1); Cirrhosis (1); Cognitive impairment (1); delirium (1); embryonal carcinoma (1); gastric cancer (1); glioblastoma (1); glioma (1); Hodgkins lymphoma (1); mast cell leukemia (1); medulloblastoma (1); metastatic disease (1).
A further 6 diseases each share a sentence with MAGEC2 in 1 paper.